AHR (aryl hydrocarbon receptor)
Diseases named in the same sentence as AHR in open-access papers (continued):
Sharing a sentence is not in itself a finding about the gene and the disease.
tumor (continued). "Since AHR possess an important implication in different physiological processes, alterations in its signaling pathway can lead to homeostatic disorders, covering from development, differentiation, pluripotence, proliferation, regeneration, tumor progression and senescence." (PMID 35465323, 2022). "Given the extensive cross-talk of the AhR with other oncogenic signaling pathways (including, e.g., PI3K/Akt, c-myc or Wnt/β-catenin-dependent signaling), there are multiple unknown factors, which may determine tumor suppressor or oncogenic role of AhR in a given tissue/cell-specific context." (PMID 36077780, 2022). "However, opposing findings have been reported by other studies which have shown that AHR can promote tumor invasiveness, but these findings are reported in the context of AHR activation by TCDD which could have adverse outcomes." (PMID 35383166, 2022). "Targeting AhR of TAMs in tumor immunotherapy may be a novel research direction." (PMID 35681736, 2022). "However, one caveat resides in the unresolved role of AhR in tumor growth and metastasis." (PMID 35173722, 2022). "Similarly, the expression level of AhR in TAMs is regulated by IDO1 in tumor." (PMID 35681736, 2022). "Thus, regulation of CYP1B1 by pathways in addition to the AHR may be important determinants to its expression and roles in tumor progression." (PMID 36077068, 2022). "TAMs may play a dual role in tumor immunity through the IDO1-Kyn-AhR pathway." (PMID 35681736, 2022). "Interestingly, recent results suggest that AhR and its interacting ligands are involved in such mechanisms that may be relevant to tumor immunotherapy." (PMID 33924971, 2021). "Taken together, these data indicate that AhR activity may promote invasive features of tumor cells." (PMID 33499346, 2021). "Furthermore, the interactions between tumor and stroma are mediated by AhR." (PMID 33499346, 2021). "Additionally, voriconazole may promote tumor development by upregulating the aryl hydrocarbon receptor-dependent COX pathway." (PMID 34066301, 2021). "Thus our current study provides valuable insights into mechanisms underlying Breg differentiation, specifically, regulation by IDO (from MDSCs and tumor cells) and by Trp metabolite L-Kyn via AhR pathway and highlight a potential link between IDO and Breg development in TME." (PMID 34867973, 2021). "Thus, natural compounds with AhR activity may be a good library for screening tumor therapeutic drugs." (PMID 34955744, 2021). "Furthermore, strategies targeting AhR activity might be beneficial in tackling immunosuppression and malignant properties of tumor cells mediated by Trp catabolites." (PMID 33924971, 2021). "In conclusion, the novel techniques we developed to characterize Trp metabolism in biological fluids as well as tumor tissue could support the identification and monitoring of patients that may benefit from therapies altering the generation of Trp metabolites or AHR activation." (PMID 34646367, 2021). "Activation of AhR signaling in the tumor microenvironment may stimulate cancer cell proliferation, and migration by enhanced expression of proangiogenic mediators and factors increased cancer cell motility, including the vascular endothelial growth factor (VEGF) and TGF-β." (PMID 33499346, 2021). "However, the effects of AhR on cell migration are diverse in different cell types, so it is difficult to define whether AhR is a tumor promoter or a suppressor." (PMID 34955744, 2021). "Moreover, targeting the IDO1/TDO2-kynurenine-AHR pathway to restore potent anti-tumor immune responses is an important goal of cancer immunotherapy, which might be highly relevant for HCC and cholangiocarcinoma therapy." (PMID 34075438, 2021). "In fact, the AhR was first known due to its implications in clinical manifestations following 2,3,7,8-tetrachlorodibenzo- p-dioxin (TCDD), a type of HAH, causing a range of toxic effects including immune suppression, tumor promotion and altered cell differentiation." (PMID 32957545, 2020).
tumor (continued). "These experiments therefore demonstrated that when TCDD activates the AHR in both the host and tumor it (i) increases the levels of ω3 epoxides in the tumors of ω3-fed mice and inhibits their growth, and (ii) enhances lung metastasis in ω6-fed mice (by an unknown mechanism)." (PMID 32398692, 2020). "In good agreement with these results, we observed that tumours bearing these genetic alterations presented higher AhR activity than tumours without, especially the AHR Q383H mutation, which displayed the highest AhR activity, supporting its gain-of-function effect." (PMID 32988402, 2020). "Thus, TCID can significantly reduce AhR protein levels and diminish tumor stem-like properties." (PMID 32546741, 2020). "However, studies are controversial, and it is still unclear whether the AHR promotes or inhibits cancer aggressiveness in any given tumor type." (PMID 33203443, 2020). "In addition, other cells that reside in the TME (e.g., dendritic cells and MDSCs) often express IDO and help tumor cells to accumulate kynurenine, which signals through the aryl hydrocarbon receptor (AhR) to promote tumor tolerance to tumor-infiltrating cytotoxic T-cells." (PMID 32630618, 2020). "Hence, it is essential to maintain proper AhR activity in IECs experiencing radiotherapy; specifically, an AhR ligand-rich diet may be considered as potentially supportive care to benefit tumor therapies in the clinic." (PMID 33322705, 2020). "Endogenous compounds may constantly activate AHR to sustain tumor promotion and progression." (PMID 32907554, 2020). "However, other lines of evidence support a tumour suppressor role for AHR in the pituitary." (PMID 31996203, 2020). "Tumour immunohistochemistry showed restriction of AHR staining to the cytoplasm, whereas both cytoplasmic and nuclear AHR staining was seen in corticotrophinoma specimens from two male patients who had non-cyclical Cushing’s disease and no AHR variants on WES." (PMID 31996203, 2020). "Although APOBEC mutagenesis was equally distributed in luminal and non-luminal BCa tumours, the AHR Q383H mutation (n = 8) occurred only in luminal BCa tumours and overall AHR genomic alterations (mutations and amplifications) and ARNT amplifications were enriched in this subtype." (PMID 32988402, 2020). "Involvement of Chr 7 by both WES and SNP array results indicated AHR copy number gain in the tumour, whilst the two different ploidy counts with Chr 8,16 tetrasomy and Chr 3,5,7,12-14,18–22 trisomy by SNP array suggested the possibility of multiple tumour clones." (PMID 31996203, 2020). "In the tumor microenvironment, tumor cells can induce IDO1 over expression, which causes the depletion of local tryptophan and the accumulation of metabolites such as kynurenine, thereby activating GCN2 and AHR signaling pathways, inhibiting T cell proliferation, and inducing apoptosis." (PMID 33101032, 2020). "Indeed, AHR-driven CYP1B1 was proposed as a universal tumor marker that could be immunologically targeted with CYP1B1-derived peptide vaccines." (PMID 33396563, 2020). "Thus, such chronic AhR activation leading to induction of MDSCs may suppress anti-tumor immunity and promote tumor development and progression." (PMID 33348596, 2020). "Thus, a possible link may be present between Malassezia metabolite-induced AHR activation and the Th17-skewed tumor immune response in EMPD." (PMID 31552251, 2019). "Furthermore, the pro- and anti-carcinogenic effects of mTOR and/or AhR activation may be a double-edged sword depending on the type of cancer, the tumor environment and the concurrent anticancer treatment." (PMID 31417567, 2019). "In addition, the discussed AHR-dependent upregulation of MMPs in UVB-exposed skin may contribute to cancer progression by fostering processes such as tumor cell migration and invasion." (PMID 31795255, 2019).
tumor (continued). "Finally, we performed multivariate analyses for the whole cohort and for patients with positive or negative LN status using the Cox regression model with total AhR expression and various clinicopathological features (age at time of diagnosis, tumor size, ER, and HER2 status)." (PMID 30813617, 2019). "Indeed, AhR is now reported to have pro- or anti-tumor activity according to cell state." (PMID 30429474, 2018). "However, AHRR has also been reported to function as a tumor suppressor independently of AHR." (PMID 28681081, 2018). "Thus, targeting the Kyn–AhR pathway (such as by inhibiting IDO1 in tumor-repopulating cell or AhR in CD8+ T cells) may enhance the efficacy of adoptive T cell therapy." (PMID 30068361, 2018). "However, studies on the role of the AhR in tumor immunity are scarce." (PMID 29487603, 2018). "Interestingly, AhR influences the major stages of tumorigenesis, and studies of aggressive tumors and tumor cell lines have shown increased levels of AhR protein and constitutive nuclear localization in cancer tissue, whereas in normal tissues AhR is mainly inactive and resides in the cytoplasm." (PMID 29706625, 2018). "Aryl hydrocarbon receptor (AhR) ligands may act as potential carcinogens or anti-tumor agents." (PMID 30522477, 2018). "Indeed, the role of AHR in inflammatory asnd neoplastic diseases has been studied extensively." (PMID 29563571, 2018). "In addition, emerging evidences suggest that AHR could play an important role in tumor growth suppression in colon cancer." (PMID 30501068, 2018). "Consequently, persistent AHR activation may lead to tumor progression and escape from tumor immune surveillance through stimulation of regulatory T cell production in the tumor environment." (PMID 30501068, 2018). "In agreement with above, novel physiological function for AhR has been proposed recently, as regulator of self-renewal of hematopoietic stem cells or in general, modulator of the balance between differentiation and pluripotentiality in normal and transformed tumor cells." (PMID 27796684, 2017). "Notably, the causal role of AhR in liver tumorigenesis gains additional support from the fact that, in AhR+/+ tumors, it was strongly repressed in the tumor proper but not in the surrounding non-tumoral parenchyma." (PMID 28874739, 2017). "Interestingly, the tumor suppressive role of AHR has been reported in several cancers." (PMID 28878246, 2017). "On the basis of these findings, it appears that the inactivation of ARNT or its partners, such as Sp1 and AhR, inhibits tumor growth; however, it may also promote metastasis, allowing tumor cells to escape from their immediate environment, such as during targeted therapy." (PMID 25839165, 2015). "Hence AhR may regulate tumor cells through both its classical nuclear transcriptional role as well as cytoplasmic non-transcriptional mechanisms." (PMID 25941627, 2015). "Therefore downregulated expression of CCL2 and VEGFA following AhR knockdown may decrease the blood supply necessary for tumor growth." (PMID 24932473, 2014). "However, AhR expression was frequently increased in more dedifferentiated tumor areas." (PMID 24755659, 2014). "In addition, there are some examples in human cancer where the tumors show increased copies of the AHR, which could increase the autocrine effect of preventing tumor clearance." (PMID 25324842, 2014). "However, the PAHs, which activate aryl hydrocarbon receptor (AhR), induce several AhR-dependent nongenotoxic effects associated with tumor promotion." (PMID 22239852, 2012). "The top five canonical pathways modulated in human tumour, based on their significance, pvalue < 0.01, included the Metabolism of Xenobiotics by Cytochrome P450, Pyrimidine Metabolism, Bile Acid Biosynthesis, Aryl Hydrocarbon Receptor Signaling and Mitotic Roles of Polo-Like Kinase." (PMID 21205295, 2011).
tumor (continued). "Particular emphasis was placed on the possibility that galangin mediates its presumptive growth regulatory effects through constitutively active tumor cell AhR and on the influence that galangin may have in altering levels of cyclins critical to maintenance of cell growth." (PMID 16569260, 2006). "This activates the aryl hydrocarbon receptor (AHR), resulting in upregulation of immunosuppressive mediators including IL-10, TGF-β, and SIGLEC15, ultimately promoting tumor immune evasion and immunotherapy resistance." (PMID 41521420, 2026). "Crosstalk between AHR and EGFR involves mutual regulation of signaling pathways that influence tumor progression." (PMID 41540003, 2026). "In summary, our results together demonstrated that I3A induces the MHC‐I expression through AhR‐JAK‐STAT3 and ERK‐c‐MYC‐STAT3 pathways on tumor cells to promote tumor immunogenicity." (PMID 40583248, 2025). "Bacteroides fragilis-derived I3A promotes barrier integrity and immune homeostasis via AhR activation, whereas Porphyromonas gingivalis-derived IAA drives immune tolerance and invasive tumor phenotypes." (PMID 40666095, 2025). "In contrast, AhR and IDO2 demonstrated hardly any correlations with clinical or tumour characteristics." (PMID 40471422, 2025). "Compared with control LNCaP xenografts, LM10-treated xenografts also significantly reduced the mRNA levels of TDO2, AhR, CYP1A1 and CYP1B1 in castration-recurrent tumours." (PMID 40759641, 2025). "Differential motif analysis nominated AHR and FOXM1 as the most significant TF motif gained by the T>C change in the MECOM promoter, and RNA-seq data analysis confirmed the expression of AHR and FOXM1 in the tumor sample." (PMID 40355593, 2025). "IAA activates the aryl hydrocarbon receptor (AHR), which subsequently blocks the NF-κB signaling pathway by competitively binding to MTDH in tumor cells." (PMID 41208900, 2025). "Mechanistically, I3A induces the activation and degradation of Aryl hydrocarbon receptor (AhR), leading to increased expression of MHC‐I molecules on tumor cell surfaces." (PMID 40583248, 2025). "The indole metabolite I3A can enhance tumor immunogenicity by targeting c‐MYC and AhR degradation, and exert T cell‐dependent antitumor effect in vivo." (PMID 40583248, 2025). "In gastric cancer, L-kynurenine, a metabolite of the amino acid l-tryptophan, mainly by IDO from tumor cells, impairs NK cells viability in TME, inducing ferroptosis in NK cells via an AhR-independent way." (PMID 40361394, 2025). "Tryptophan‐derived metabolites activate AHR, promote tumour progression, and regulate the TME in different tumours, including GBM." (PMID 40071723, 2025). "The deregulation of the AhR pathway and its byproducts in the TME facilitates immune evasion, which in turn helps the tumor to evolve." (PMID 40650089, 2025). "At physiological concentrations (e.g., approximately 5 μM in tumor tissues), ICA acts as a competitive partial AhR agonist, binding to AhR with higher affinity than the immunosuppressive ligand Kyn." (PMID 41181090, 2025). "Liu's study revealed that in tumor‐repopulating cells (TRCs), IFN‐γ‐induced IDO1 promotes p27 transcription and expression via the kyn/AhR pathway." (PMID 40103267, 2025). "In contrast, both AhR and IDO2 had hardly any correlation with patient, blood or tumour characteristics." (PMID 40471422, 2025). "Depletion of dietary tryptophan reduces AhR activity in TAMs, promoting the accumulation of TNF-α+IFN-γ+CD8+ T cells within the tumor and slowing tumor progression." (PMID 39905317, 2025). "The aromatic hydrocarbon receptor (AHR), a ligand-activated transcription factor involved in the regulation of tumor proliferation, invasion, metastasis, and immune escape, has recently become a star target for cancer therapy." (PMID 39948481, 2025). "Tryptophan metabolite Indole‐3‐aldehyde (I3A) downregulates cytosolic AhR and p‐ERK/c‐MYC proteins, together enhancing STAT3 phosphorylation and tumor immunogenicity." (PMID 40583248, 2025).
tumor (continued). "Subsequent activation of AhR leads to an upregulation of IL-6 secretion, further promoted by the STAT3 and TIM4/NF-κB signaling pathways, ultimately inducing tumor progression." (PMID 40136551, 2025). "Further investigation found that I3A induced tumor immunogenicity depending on down‐regulation of c‐MYC and AhR, two key transcription factors involved in cancer metabolism, leading to increased expression of MHC‐I and antigen presentation machinery molecules." (PMID 40583248, 2025). "CYP1A1, another AhR target gene, showed elevated protein levels in two of three late-stage CRC tumours, aligning with earlier studies." (PMID 40348885, 2025). "This enzymatic activity establishes an immunosuppressive tumor microenvironment via two distinct pathways: GCN2-mediated T cell anergy resulting from tryptophan depletion, and AhR-dependent immune tolerance induced by accumulating kynurenine metabolites." (PMID 40894232, 2025). "Another study reveals a critical microbial-host crosstalk between Lactobacillus-released aryl hydrocarbon receptor (AhR) agonist indole-3-aldehyde (I3A) and CD8+ T cells within the tumor microenvironment." (PMID 41208998, 2025). "Inhibition of TDO expression diminishes kynurenine production and inactivates the aryl hydrocarbon receptor (AhR), thereby promoting the activation and proliferation of CD3(+) T cells, which contribute to anti-tumor immune responses." (PMID 39940736, 2025). "Using the same murine SCC7 tumor model, intratumoral administration of F.n. outer membrane vesicles promoted tumor growth by suppressing CD8+ T cell infiltration and increasing AHR-positive macrophages." (PMID 40924302, 2025). "The intelligent HMP1G NPs respond to H+ and glutathione in the tumor microenvironment (TME), They downregulate tumor‐derived IDO1 via the AhR/STAT3/IL axis, improve the KYN/TRP metabolic imbalance, and effectively counter immunosuppression in the TME." (PMID 39661740, 2025). "Xu's experiment revealed that SRF promotes EMT and increases tumor migration and invasion in OSCC cells by activating the IDO1 gene promoter and regulating the IDO1/Kyn‐AhR signaling pathway." (PMID 40103267, 2025). "A study by Christiane A. Opitz and colleagues identified, through screening and analyzing a broad range of tumor cases, the highest correlation between IL4I1 and AHR activity." (PMID 38755125, 2024). "TDO2-produced tryptophan can increase the activation of aryl hydrocarbon receptor (AhR) in TNBC, thereby promoting the proliferation, invasion, and metastasis of cancer cells and directly inhibiting the anti-tumor activity of T cells." (PMID 38680483, 2024). "Activation of AHR has been shown to lead to the phosphorylation of AKT, a downstream effector of the PI3K pathway, thereby promoting tumor cell proliferation and chemotherapy drug resistance." (PMID 39835132, 2024). "Inhibition of AhR restored the inflammatory phenotype of macrophages and promoted the infiltration of IFNγ+CD8+T cells, which weakened Ahr-dependent tumor growth." (PMID 38279145, 2024). "In TME, the expression of AhR in CAF and TAM is closely related to metabolism and tumor progression." (PMID 38434684, 2024). "FGF2 indirectly promotes the secretion of CXCL14 through the activation of FGFR1/ERK/aryl hydrocarbon receptor (AHR) signaling cascade from pericytes, which in turn induces M2 polarization of TAMs and promotes tumor metastasis." (PMID 38962005, 2024). "IL4I1 is associated more frequently than IDO1 or TDO2 with the activity of aryl hydrocarbon receptor (AHR), a ligand-activated transcription factor that can sense tryptophan (Trp) catabolites, enhancing tumor malignancy and suppressing antitumor immunity." (PMID 39516356, 2024). "AHR also dysregulates BRCA1 expression, a crucial tumour suppressor in HGSOC and is additionally correlated with an unfavourable prognosis in OC." (PMID 38361045, 2024).